IL6 (interleukin 6)
Diseases named in the same sentence as IL6 in open-access papers (continued):
Sharing a sentence is not in itself a finding about the gene and the disease.
Insulin resistance (continued). "HFB-fed mice showed signs of impaired glucose metabolism and insulin resistance along with a significant elevation in the concentration of triglycerides, LDL-cholesterol, total cholesterol, IL1β, TNF-α, IL-6, and leptin in serum." (PMID 30319558, 2018). "This indicate inflammatory role of PST in inducing IL-6 and MCP-1 production and insulin resistance." (PMID 29880906, 2018). "A number of epidemiological and animal studies have examined the relationship between hepatic insulin resistance and increased production of inflammatory factors such as TNF-α and IL-6." (PMID 29709004, 2018). "Liver insulin resistance leads to increased production of glucose, lipoproteins, inflammatory factors such as TNF-α and interleukin 6 (IL-6), and coagulation factors such as fibrinogen A (FGA), fibrinogen B (FGB) and plasminogen activator inhibitor-1 (PAI)." (PMID 29709004, 2018). "In this sense, prior studies suggest a positive relationship between markers of chronic inflammation, including CRP, IL-1β, IL-6, and TNF-α, and insulin resistance." (PMID 29561774, 2018). "To study the influence of inflammation on hepatic insulin resistance, we determined the levels of MCP-1, C-reactive protein (CRP), IL-6 and TNF-α." (PMID 29028831, 2017). "Increased level of IL-6, TNF-α and CRP are thought to contribute to the development of insulin resistance, T2DM, and CVD." (PMID 28125601, 2017). "This study aimed to evaluatethe therapeutic effects of curcumin on IL-6 and CRP levels as well as insulin resistance(IR) index on liver function in PCOS rats." (PMID 28836404, 2017). "Plasma IL-6, CRP, glucose, serum insulin, and homeostasis model assessment of insulin resistance were significantly greater in OO compared with OL and YL (P < 0.01)." (PMID 28911148, 2017). "These immune regulatory cells synthesize and release proinflammatory cytokines such as IL-1, IL-6, and TNF-α which are regarded as the key factors involved in metabolic dysregulation including glucose and lipid disorders and insulin resistance in T2D." (PMID 28396851, 2017). "Plasma ceramides have also been shown to correlate with levels of the inflammatory cytokines TNF-alpha and IL6 and have been suggested to be the mediator behind TNF-alpha-induced insulin resistance." (PMID 28545587, 2017). "Ginsenoside Rb1 reduced free fatty acids in the blood and fat content, improved lipid metabolism and insulin resistance, and inhibited TNF-α, IL-6, and other inflammatory factors in obese mice." (PMID 29164155, 2017). "Elevated levels of IL-6 and CRP levels among individuals with features of the insulin resistance and type 2 diabetes have been apparent." (PMID 28555043, 2017). "High-fat diets not only elevated the hepatic free fatty acid levels associated with non-alcoholic fatty liver disease through cellular oxidative stress, but also led to insulin resistance related to hepatic tumor necrosis factor (TNF)-α and interleukin-6." (PMID 29048361, 2017). "M1 macrophages act in the production of proinflammatory cytokines, such as IL-1β, IL-6, and TNF-α, which provoke the development of insulin resistance in adipocytes." (PMID 29077020, 2017). "We also used siRNA to determine the mechanisms and the crosstalk between IL-6 and TLR4 expression via STAT3 in the development of insulin resistance and glucose intolerance in the skeletal muscle." (PMID 28706484, 2017). "In humans, there is a positive correlation between serum PGRN and IL-6 and HOMA-IR index (Homeostasis Model Assessment for insulin resistance)." (PMID 27776152, 2016). "Proinflammatory immune mediators, like IL-1β, IL-6, or TNF-α, are important factors in the development of insulin resistance." (PMID 27069930, 2016). "Most studies found that subjects with insulin resistance, prediabetes, or T2DM had increased levels of IL-6, TNF-α, and hs-CRP." (PMID 27478850, 2016).
Insulin resistance (continued). "Systemic inflammation, with elevated markers such as C-reactive protein (CRP), tumor necrosis factor-α (TNF-α) and interleukin-6 (IL-6), plays an important role in both, the progression of COPD and the development of insulin resistance." (PMID 27335596, 2016). "Exercise increases the secretion of interleukin-6 (IL-6) from muscle cells, which has anti-inflammatory effects through inhibition of TNF-α and IL-1β, and reduces TNF-induced insulin resistance." (PMID 27485519, 2016). "CCL2 plays a crucial role in the recruitment of macrophages into WAT and upregulation of TNF-α, IL-6 and CCL2 in WAT is critically involved in the induction of systemic insulin resistance." (PMID 26871288, 2016). "Ceramides like reconstituted low density lipoprotein ceramide 24:0 were found to increase TNF-α, IL-1β, IL-6, and MCP-1 in vitro and to induce insulin resistance in lean mice." (PMID 26788518, 2016). "Similar results were observed in whole body Wnt5a knockout mice, which showed that Wnt5a ablation attenuated high-fat/high-sucrose (HFHS)-induced insulin resistance, and these mice displayed decreased expression of TNF-α, CCL2, and IL-6 in adipose tissue." (PMID 27608847, 2016). "M1 macrophages accumulated in adipose tissue produce various inflammatory mediators such as IL-6 and TNF-α and promote the development of insulin resistance." (PMID 25816341, 2015). "Our finding in this study revealed that FDW consumption, in a month, induced insulin resistance index (IRI), hyperinsulinemia a serum proinflammatory cytokines values such as IL6 and TNF in male rats." (PMID 26170888, 2015). "In addition, we also showed a significant positive correlation between some clinical and laboratory variables, including hypertension and the levels of IL-6 and resistin which are adipocytokines that may contribute to insulin resistance and to the development of inflammatory responses." (PMID 25883983, 2015). "As an anti-inflammatory cytokine, IL-6 was reported to inhibit the effects of proinflammatory TNF-α, promote M2 macrophage polarization, and improve insulin resistance." (PMID 26200663, 2015). "Obese mice showed insulin resistance, decreased expression of Slc2a4 mRNA (66%, P < 0.01) and GLUT4 protein (30%, P < 0.05), and increased expression of interleukin 6 (Il6) mRNA (44%, P < 0.05) in SAT." (PMID 25834641, 2015). "In obese subjects, macrophages infiltrate into livers and adipose tissue and secrete pro-inflammatory cytokines (including IL-6 and TNF-α) and lead to insulin resistance." (PMID 26519255, 2015). "Increased concentration and expression of TNF-α, interleukin-6 (IL-6), and monocyte chemoattractant protein-1 (MCP-1) are evident in adipocyte dysfunction and insulin resistance." (PMID 25650336, 2015). "In addition, we also showed a significant positive correlation between some clinical and laboratory variables, including dyslipidemia and the levels of IL-6 and resistin which are adipocytokines that may contribute to insulin resistance and to the development of inflammatory responses." (PMID 25883983, 2015). "In fact, some studies have reported abnormally high circulating levels of inflammatory cytokines including IL-6, IL-8, IFN-γ, and TNF-α in obese individuals exhibiting OSA and insulin resistance/type 2 diabetes." (PMID 25944984, 2015). "No significant intervention effect was observed for adiponectin, insulin resistance, or inflammatory markers (CRP, IL-6 and TNF-a) although the findings were inconclusive." (PMID 25706622, 2015). "ATMs, a major source of inflammatory mediators such as TNF-α and IL-6, play critical role in WAT inflammation and in the development of insulin resistance." (PMID 25816341, 2015). "Additionally, increases in free fatty acids (FFA), interleukin (IL)-6, tumor necrosis factor (TNF)-alpha, together with other pro-inflammatory cytokines that occur with adipose tissue inflammation and changes in adipose tissue function are also associated with insulin resistance." (PMID 26893932, 2015).
Insulin resistance (continued). "Plasma IL-6, IL-8, and MCP-1 levels are considerably enhanced in obese humans and in patients with insulin resistance, type 2 diabetes, and cardiovascular diseases." (PMID 25926797, 2015). "In the present study, we did not report any significant difference in protein expression of TNF-alpha, IL-6 and SOCS3 during HFD-induced cardiac insulin resistance." (PMID 26539824, 2015). "This study demonstrated that OA attenuated insulin resistance in HepG2 cells, whose effect is possibly mediated through decreasing the levels of TNF-α and IL-6 and regulating the expression of IRS1 and GLUT4 protein via the NF-κB protein." (PMID 26843885, 2015). "CLE significantly decreased fasting blood glucose, glucose level in OGTT and IPITT, plasma insulin, homeostatic model assessment-insulin resistant (HOMA-IR), TNF-α, IL-6, FFA, TG and TC levels, and hepatic glycogen content in db/db mice." (PMID 25889508, 2015). "Adipocyte dysfunction and its associated adipocyte cell hypertrophy and production of pro-inflammatory cytokines, such as interleukin 6 (IL-6) and tumor necrosis factor alpha (TNF-α), also contribute to the development of insulin resistance and T2D." (PMID 26407933, 2015). "Correspondingly, TNF-α concentration correlated with the degree of stunting in girls, and IL-6, CRP and insulin resistance correlated with the degree of stunting and adiposity in boys in South Africa." (PMID 26445018, 2015). "Exercise confers protection against TNF-α induced insulin resistance while it reduces CRP, IL-6, and TNF-α levels and increases anti-inflammatory substances such as IL-4 and IL-10." (PMID 24563869, 2014). "IL-6 and TNF-α contribute to liver production of CRP and atherosclerosis by inducing insulin resistance and upregulating the expression of other inflammatory mediators." (PMID 24744504, 2014). "This study was designed to investigate the complex role of IL‐6 on HFD‐induced glucose intolerance, and the response to voluntary physical activity in the prevention of insulin resistance." (PMID 24997069, 2014). "Elevated circulating levels of tumor necrosis factor-α (TNF-α), interleukin-6 (IL-6), and high-sensitivity capsular reactive protein (hs-CRP), which can impair insulin resistance and thereby reduce glycemic control, have been shown in a previous study." (PMID 25147841, 2014). "Visceral fat mast cells from obese patients were found to produce significantly higher proinflammatory cytokines (IL-1, IL-6) and macrophage chemoattractant (MCP-1) previously shown to induce insulin resistance." (PMID 24823865, 2014). "Insulin resistance is known to be induced by inflammation arising from adipose tissue and elevated levels of CRP and IL-6 are shown to predict the development of diabetes." (PMID 25337037, 2014). "Adipocytes secrete substances that contribute to peripheral insulin resistance, including adiponectin, resistin, TNF-alpha and interleukin 6 which interfere with glucose metabolism and exert lipotoxic effects on pancreatic beta cells." (PMID 25374160, 2014). "To date, a range of adipokines (e.g., IL-6, TNF-α and resistin) have been reported to promote insulin resistance in adipocytes through the STAT3-SOCS3 pathway." (PMID 24516630, 2014). "It has been reported that insulin resistance and cytokines such as TNF-α, IL-1, IL-2, IL-6, PAF raise serum triglyceride levels while reduce total and HDL-cholesterol levels." (PMID 24772131, 2014). "Conversely, adoptive transfer of CD8+ T cells into CD8-deficient mice increased infiltration of macrophages into VAT as well as expression of the inflammatory cytokines IL-6 and TNF-α, along with development of insulin resistance following high-fat diet." (PMID 25157251, 2014). "Several studies suggest that TNF-α and IL-6 improve lipolysis and the secretion of FFA, which promotes insulin resistance by interfering with glucose transport and insulin action." (PMID 25053966, 2014).
Insulin resistance (continued). "After adjusting for age and gender, SMI and CRF tended to be negatively correlated with most of the markers for insulin resistance and chronic inflammation, including HOMA-IR, hsCRP, IL-6, leptin, and the number of metabolic syndrome components." (PMID 24937121, 2014). "In conclusion, this study utilized the IL‐6 KO model to investigate the role of IL‐6 on HFD‐induced glucose intolerance, and the response to voluntary physical activity in the development of insulin resistance." (PMID 24997069, 2014). "It is known that TNF-alpha, IL-6, and CRP play an important role in insulin resistance and the vascular inflammation process through their multiple actions." (PMID 24249586, 2014). "Many pro-inflammatory cytokines, such as TNF-α, IL-6 and IL-1β, have been demonstrated to be elevated in T2DM patients and participate in the development of insulin resistance." (PMID 24759263, 2014). "Inflammatory molecules generated in adipose tissue, such as TNF-α and IL-6, are related to decreased GLUT4 expression, which leads to insulin resistance due to decreased adipocyte glucose uptake." (PMID 24398136, 2014). "Hyperinsulinaemia and hepatic insulin resistance and steatosis is promoted by increased JNK-1 signalling (via IL-6) in adipose tissue and it is purported that adipose tissue-derived mediators are a major source of damaging cytokines in NASH." (PMID 24830559, 2014). "This study was designed to investigate the role of interleukin‐6 (IL‐6) on high‐fat diet (HFD)‐induced glucose intolerance, and the response to voluntary physical activity in the prevention of insulin resistance." (PMID 24997069, 2014). "Obese B cell null mice had decreased inflammatory cytokines, including IL-6 and IFN-γ, increased anti-inflammatory IL-10 levels, and protection against insulin resistance compared to obese wildtype mice." (PMID 25157251, 2014). "Complete phenotypic characteristics of both dietary groups exhibited differences in most relevant parameters including fat masses, homeostatic model assessment-insulin-resistance (HOMA-IR), and plasma IL-6 and UA levels." (PMID 23826106, 2013). "It must be noted that leptin, IL6 and TNF are pro-inflammatory cytokines with a recognised role in the development and progression of insulin resistance, T2DM and cardiovascular disease." (PMID 23298335, 2013). "Immunological or genetic depletion of CD8+ cells reduces macrophage infiltration, adipose tissue release of proinflammatory mediators (such as IL1, IL6 and MCP-1), and insulin resistance." (PMID 24084730, 2013). "By univariate analysis, epicaridal fat volume is correlated with coronary artery calcification, body mass index, dyslipidemia, insulin resistance (HOMA-IR), abdominal obesity, albuminuria and interleukin-6." (PMID 23351146, 2013). "This suggests the inverse relationship of circulating adiponectin levels to IL-6 and TNF-α and insulin resistance in critically ill patients." (PMID 23840093, 2013). "An increase of IL-6 (p = 0.015) and TNF (from 49.7 to 53 pg/mL), and decrease of plasma APO (7658 to 5152 ng/mL) and exacerbation of insulin resistance (p = 0.007) were noted." (PMID 22829443, 2013). "Inflammatory cytokines such as IL-6, IL-1β, MCP-1 and TNF- α, produced by fat, liver, muscle, and inflammatory cells, have been described as key players in obesity, insulin resistance and diabetes." (PMID 23527073, 2013). "BMI, abdominal obesity, HDL cholesterol, triglycerides, insulin resistance (log HOMA-IR), markers of inflammation (log IL-6, log hsCRP, hypoalbuminemia and albuminuira) and log CAC score demonstrated the strongest associations with ssEFV." (PMID 23351146, 2013). "In WAT of KK-Ay mice fed fucoxanthin, mRNA expression levels of pro-inflammatory adipocytokines, such as interleukin-6 (IL-6) and tumor necrosis factor-α (TNF-α), which are thought to induce insulin resistance, were markedly suppressed." (PMID 23820585, 2013).
Insulin resistance (continued). "Resistin, another adipokine, has been shown to have an insulin resistance-inducing effect and to induce inflammation via stimulation of TNF-α and IL-6 production by monocytes." (PMID 23598440, 2013). "In cultured murine adipocytes, IL-6 production is strongly increased by TNF-α and induces insulin resistance by inhibiting glucose uptake and impairing insulin signaling and action." (PMID 24455420, 2013). "Two important insulin resistance-related inflammatory cytokines namely TNF-α and IL-6 produced by adipose tissue were evaluated by commercially available ELISA kit." (PMID 23590862, 2013). "Adipokines enlisted in regulation of insulin resistance are adiponectin, leptin, resistin, visfatin, chemerin, TNF-α, IL-1, IL-6, IL-8, IL-10, plasminogen activator inhibitor 1, monocyte chemoattractant protein-1, and retinol binding protein-4." (PMID 24455420, 2013). "Adipocytes produced IL-6 via TLR4 activation and the upregulation of osteopontin further exacerbated adipose tissue inflammation and insulin resistance." (PMID 23191980, 2012). "It has been shown that IL-6 suppresses the production of TNF-α, a cytokine involved in the pathogenesis of insulin resistance and CVD." (PMID 22272193, 2012). "Consistent with this, elevated levels of the proinflammatory cytokines TNF-α, IL-6, and C-reactive protein (CRP) have been shown in individuals with insulin resistance and diabetes." (PMID 22804097, 2012). "In keeping with recent work from Febbraio's group, we found that IL-6 deficient mice were more glucose and insulin intolerant than WT controls when fed a HFD, demonstrating that IL-6 may play a protective role against the development of insulin resistance in conditions of chronic nutrient excess." (PMID 23240005, 2012). "Activation of proinflammatory pathways and secretion of cytokines such as interleukin-6 (IL-6), plasminogen-activator inhibitor-1, and free fatty acids (FFA) have been suggested to produce insulin resistance." (PMID 22701480, 2012). "In moderate dose endotoxemia, we observed strong induction of subcutaneous adipose TNF and IL-6 as well as MCP-1, which is known to recruit CCR-2 expressing monocytes, increase inflammatory-M1 adipose tissue macrophage (ATM) and promote insulin resistance." (PMID 22709547, 2012). "Parameters of liver steatosis, glutathione status, protein carbonylation, and fatty acid analysis were determined, concomitantly with insulin resistance and serum tumor necrosis factor-α (TNF-α), interleukin (IL)-1β, and IL-6 levels." (PMID 23082120, 2012). "In visceral obesity, adipocytokines such as TNFα, resistin, IL-6 and FFA are secreted by enlarged fat cells of the internal organs as adipose tissue and induce insulin resistance." (PMID 22348333, 2012). "There is evidence that insulin resistance results from the proinflammatory cytokines actions released from the adipose tissue, such as TNF-α and IL-6." (PMID 21352586, 2011). "Out of the insulin-resistance mediating factors, plasminogen activator inhibitor-1 (PAI-1), MCP-1, IL-6, IL-8, IL-10 and tumour necrosis factor (TNF)-α were significantly elevated in these patients." (PMID 21470423, 2011). "The molecular pathways that link inflammation and insulin resistance include a variety of cytokines and adipocytokines such as TNF-α, IL-6, MCP-1, leptin, and adiponectin." (PMID 21403905, 2010). "A possibility is therefore that cytokines, such as interleukin (IL)-6 and tumor necrosis factor (TNF)-α, contribute to the development of insulin resistance and impaired islet function." (PMID 20529356, 2010). "A better understanding of the molecular mechanisms utilized by saturated NEFA and insulin to regulate IL-6 production in proinflammatory monocytes could identify targets for novel anti-inflammatory molecules that could reduce the incidence of complications from insulin resistance." (PMID 21054880, 2010).